CRYZL1 (crystallin zeta like 1)
Description:
Component of the FERRY complex (Five-subunit Endosomal Rab5 and RNA/ribosome intermediary). The FERRY complex directly interacts with mRNAs and RAB5A, and functions as a RAB5A effector involved in the localization and the distribution of specific mRNAs most likely by mediating their endosomal transport. The complex recruits mRNAs and ribosomes to early endosomes through direct mRNA-interaction.
Synonyms: Fy-4; QOH-1; 4P11; FERRY4
Tractability: PROTAC: ubiquitination databases record sites on it; its protein half-life has been measured.
Gene: Protein-coding gene on chromosome 21 (33,589,341 to 33,643,926, reverse strand). Ensembl gene ENSG00000205758.
Subcellular location: Early endosome
Subcellular location (Human Protein Atlas): Cytosol; Nucleoplasm
Gene Ontology:
Molecular function: identical protein binding; protein binding; oxidoreductase activity
Biological process: regulation of intracellular mRNA localization
Cellular component: cytosol; early endosome
Genetic constraint (gnomAD): Loss-of-function variants: 9 observed, 19.33 expected, observed/expected ratio (o/e) 0.47, 90% interval 0.28 to 0.81. The upper end of that interval is the gene's LOEUF score, 0.81, which puts it in group 3 of 6, group 1 being the genes least tolerant of losing a copy. Missense variants: 152 observed, 178.84 expected, observed/expected ratio (o/e) 0.85, 90% interval 0.74 to 0.97. Synonymous variants: 57 observed, 63.62 expected, observed/expected ratio (o/e) 0.9, 90% interval 0.72 to 1.12.
Homologues: Orthologues: macaque CRYZL1 (99% identical), chimpanzee CRYZL1 (98% identical), chimpanzee CRYZL1 (96% identical), pig CRYZL1 (94% identical), rabbit CRYZL1 (94% identical), dog CRYZL1 (94% identical), guinea pig CRYZL1 (91% identical), mouse Cryzl1 (91% identical), rat Cryzl1 (89% identical), tropical clawed frog cryzl1 (66% identical), zebrafish cryzl1 (59% identical), Caenorhabditis elegans D2063.1 (15% identical), and 2 more. Paralogues in human: TP53I3 (22% identical), RTN4IP1 (21% identical), VAT1 (21% identical), VAT1L (20% identical), CRYZ (19% identical), PTGR3 (18% identical), SORD (17% identical), ADH4 (17% identical), ADH5 (17% identical), ADH1A (16% identical), MECR (16% identical), ADH1B (16% identical), and 5 more.
Diseases named in the same sentence as CRYZL1 in open-access papers:
CRYZL1 is named in the same sentence as 3 diseases in open-access papers, as found by Europe PMC text mining. Sharing a sentence is not in itself a finding about the gene and the disease. The quoted sentences say what the papers report.
cervical cancer (2 papers, 2021 to 2025). A primary or metastatic malignant neoplasm involving the cervix. "Finally, within a group of cervical cancer tumor samples, differential methylation of CRYZL1 was associated with cervical cancer survival risk." (PMID 40062705, 2025).
Neurologic disorders (1 paper, 2025). "Neurologic disorders have yet to be associated with mutation of GATD1 or CRYZL1." (PMID 40062705, 2025). "Mutation of the remaining two members of the FERRY complex, glutamine amidotransferase-like class 1 domain containing 1 (GATD1) and crystallin, zeta (quinone reductase)-like 1 (CRYZL1) has not yet been associated with neurologic disease." (PMID 40062705, 2025).
CRYZL1 also shares sentences with these, for which no sentence is quoted: Stroke (1 paper).